MALAT1 (metastasis associated lung adenocarcinoma transcript 1)
Diseases named in the same sentence as MALAT1 in open-access papers (continued):
Sharing a sentence is not in itself a finding about the gene and the disease.
steatosis (3 papers, 2018 to 2025). Increased lipid within the cytoplasm of cells. "MALAT1 mRNA expression was quantified in untreated HepG2 cells, steatosis-induced cells, OA+Ex-4-treated cells, and Ex-4-alone-treated cells." (PMID 40002783, 2025). "In conclusion, the present study proposes that the improvement in OA-induced steatosis in response to Ex-4 involves the regulation of the expression of several genes, and that this regulation is mediated through MALAT1." (PMID 40002783, 2025). "The present study is the first to examine the role of the lncRNA MALAT1 in the protective effect of the GLP-1RA Ex-4 on steatosis induced by OA in HepG2 cells." (PMID 40002783, 2025). "To further investigate the role of MALAT1 in the protective effect of Ex-4 on steatosis, we quantified the expression of the SREBP-1 and PPARγ genes, known for their role in de novo lipogenesis." (PMID 40002783, 2025). "To better understand the potential role of MALAT1 silencing as a molecular determinant through which Ex-4 mediates its beneficial effect on steatosis, we quantified SREBP1, PPRAδ, FAS, SCD1, ACC, and MTTP at the protein level before and after silencing." (PMID 40002783, 2025). "Although some LncRNAs, such as MALAT1, H19, and NEAT1, were previously associated with NAFLD, the association of others with steatosis and the positive effect of Ex-4 is being reported for the first time." (PMID 34078383, 2021). "The expression of the LncRNA MALAT1 was also significantly upregulated by OA induced steatosis and downregulated by treatment with Ex-4." (PMID 34078383, 2021). "Concordant with these findings, a recent study reported that hepatic MALAT1 expression was higher in NASH patients when compared to NAFLD patients with simple steatosis and controls." (PMID 30134610, 2018). "The Ex-4-induced down-regulation of MALAT1 in our study may, therefore, play s a critical role in the steatosis improvement we observe upon Ex-4 treatment." (PMID 34078383, 2021). "Levels of MALAT1 in paired liver biopsies taken at least five years apart showed an eight-fold increase in one patient who progressed from steatosis to NASH fibrosis and a 29-fold increase in another patient who progressed from fibrosis 0 (no fibrosis) to fibrosis 3 (advanced fibrosis)." (PMID 30134610, 2018). "The effect of MALAT1 silencing on DGAT1 expression in the presence of Ex-4 suggests that Ex-4 reduces OA-induced steatosis by a mechanism that implicates the deactivation of DGAT1, and, thus, TG synthesis, via the modulation of MALAT1." (PMID 40002783, 2025). "Although the role of MALAT1 and the impact of GLP-1RAs in steatosis have not yet been examined in vivo, there is substantial evidence supporting their ability to reduce the liver fat content in both animal models and patients with NAFLD." (PMID 40002783, 2025).
tongue cancer (3 papers, 2018 to 2023). A malignant neoplasm affecting the tongue. "Liang and team identified the role of lncRNA metastasis-associated lung adenocarcinoma transcript 1 (MALAT1) in enhancing tongue cancer cell proliferation through canonical Wnt signaling modulation." (PMID 37888209, 2023). "For instance, JAG1 is modulated by MALAT1/miR-125 signaling to promote tongue cancer development." (PMID 33292218, 2020). "Additionally, it is verified that the interaction between MALAT1 and miR-124 also plays a critical part in tongue cancer cell growth, and miR-124 has been previously confirmed to be associated with HR-HPV-positive cervical cancer and breast cancer." (PMID 29416703, 2018). "Another investigation indicated that lncRNA MALAT1 promotes EMT and inhibits apoptosis in tongue cancer cells through the WBC signaling modulation." (PMID 37888209, 2023).
vitiligo (3 papers, 2021 to 2024). Generalized well circumscribed patches of leukoderma that are generally distributed over symmetric body locations and is due to autoimmune destruction of melanocytes. "Significant results have been obtained from research conducted by various groups, which identified the lncRNA metastasis-associated lung adenocarcinoma transcript 1 (MALAT1) as being involved in protecting the amelanotic keratinocytes of vitiligo patients from UV radiation." (PMID 39735711, 2024). "miR-211 is one of those miRNAs recently shown to be downregulated in lesioned epidermis samples from vitiligo patients in relation with increased expression of a lncRNA, MALAT1, which sequesters miR-211, enhancing SIRT1 expression." (PMID 35883477, 2022).
adenoma (2 papers, 2019 to 2022). A neoplasm arising from the epithelium. "Briefly, a general feature of the first group was the gain in adenoma tissue of chromosome 11, 11q13.1, encoding long non-coding RNA (lncRNA) MALAT1 and its antisense transcript TALAM1, in patients P1, P2, P3, P5, and P16." (PMID 35887000, 2022). "Since long non-coding RNA MALAT1 is associated with cancer cell metastasis and migration, its gene amplification represents an important event for adenoma development." (PMID 35887000, 2022). "In the adenoma genome of patient P5, trisomy of three chromosomes (chr: 7 (α^ = 23%), 13 (α^ = 22%) and X (α^ = 11%)) was found, and at the same time gain of the region encoding for MALAT1 and TALAM1 (α^ = 100%)." (PMID 35887000, 2022). "Therefore, we concluded that amplification of the region encoding MALAT1 and TALAM1 in 5 out of the 16 adenoma samples revealed cancer potential in these samples." (PMID 35887000, 2022). "The second group consisted of patients with numerous chromosomal microdeletions in adenoma tissues compared to the adjacent tissue with no aberrations in the region encoding for MALAT1 or TALAM1 (P6, P7, and P10)." (PMID 35887000, 2022). "Our hypothesis is that amplification of MALAT1 already in adenoma tissue could be a precursor of cancer development." (PMID 35887000, 2022). "Common features of patients P6, P7 and P10 in this second group were many microdeletions at 7q, 9p, 16p, 17q, and 20q in the genome of adenoma tissue compared to that of adjacent tissue, and likewise without the presence of MALAT1 or TALAM1 gain on chromosome 11 or any other gain." (PMID 35887000, 2022).
aortic valve calcification (2 papers, 2023 to 2025). "Multiple lncRNA-mediated miRNA–mRNA networks, such as the TUG-miR-204-5p-Runx2 and MALAT1-miR-191-3p-HuR networks, have been reported to be implicated in aortic valve calcification." (PMID 40937116, 2025).
atrophic gastritis (2 papers, 2020 to 2022). "We found that the CT genotype of rs3200401 in MALAT1 gene and a recessive model for rs1333045 (ANRIL) were significantly associated with risk of atrophic gastritis." (PMID 33333725, 2020). "Carriers of CT genotype of rs3200401 (MALAT1) analyzed had higher odds of atrophic gastritis than those with CC genotypes (OR-1.81; 95% CI 1.17–2.80, p = 0.0066)." (PMID 33333725, 2020). "Results showed that carriers of MALAT1 rs3200401 CT genotype had the significantly higher odds of atrophic gastritis than those with CC genotype (OR-1.81; 95% CI 1.17–2.80, p = 0.0066)." (PMID 33333725, 2020).
brain cancer (2 papers, 2024 to 2025). A primary or metastatic malignant neoplasm affecting the brain. "Some of the most representative lncRNAs, such as HOTAIR, MALAT1, and MEG3, have been consistently validated over the years, where their role in malignant brain tumors appears evident." (PMID 41149459, 2025).
brain tumor (2 papers, 2018 to 2024). "Both HOTAIR and MALAT1 are upregulated in and promote brain tumor metastasis, and Malat1 regulates synaptogenesis in mouse hippocampal neurons by controlling gene expression." (PMID 30344479, 2018). "Future advancements in nano-formulations may enhance the delivery of MALAT1-targeting agents to brain tumors, underscoring the significance of investigating and targeting MALAT1 in GBM pathogenesis." (PMID 39553554, 2024). "Interestingly, blocking MALAT1 expression enhances the permeability of the blood-brain tumor barrier by miR-140, which in turn facilitates the distribution of chemotherapy agents into GBM tissues." (PMID 39553554, 2024).
cataract (2 papers, 2016 to 2020). Partial or complete opacity of the crystalline lens of one or both eyes that decreases visual acuity and eventually results in blindness. "Consistent with previous studies, we also found that MALAT1 was aberrantly expressed in LECs of diabetic cataract patients and in high glucose conditions." (PMID 33274006, 2020). "The expression of MALAT1 level in the LECs of diabetic cataracts was significantly increased compared with age-related cataracts (CON)." (PMID 33274006, 2020). "In the present study, we first confirmed that MALAT1 and NRF2 are highly expressed in LECs of diabetic patients with cataracts and in LECs in a hyperglycemic environment." (PMID 33274006, 2020).
cerebral palsy (2 papers, 2020 to 2023). A group of disorders affecting the development of movement and posture, often accompanied by disturbances of sensation, perception, cognition, and behavior. "Previous studies have shown that MALAT1 can inhibit apoptosis by upregulating BDNF expression through suppression of miR-382-3p in the central neurons of cerebral palsy mice." (PMID 37740187, 2023). "Vitamins B1 and B12 upregulate brain-derived neurotrophic factor (BDNF) expression and its downstream PI3K/Akt signaling pathway through the MALAT1/miR-1 axis, thereby inhibiting neuronal apoptosis and reducing nerve damage in cerebral palsy rat models." (PMID 33192306, 2020).
chronic hepatitis B (2 papers, 2022 to 2025). "For instance, MALAT1 was linked to liver inflammation through activation of the NLRP3 inflammatory complex in patients with chronic hepatitis B and NAFLD." (PMID 40002783, 2025).
chronic lung disease (2 papers, 2022 to 2023). According to the definitions of the American and British Thoracic Societies, including pulmonary functional tests, X-rays, and CT scans for items such as fibrosis, bronchiectasis, bullae, emphysema, nodular or lymphomatous abnormalities. "In this review, we collected the evidence to discuss MALAT1 effects on ALI and chronic lung diseases, altogether describing the roles of MALAT1 in inflammation responses, cell apoptosis, cell proliferation, and airway remodeling." (PMID 36186445, 2022). "Besides, we also found a MALAT1-miRNA-mRNA ceRNA regulatory network in acute and chronic lung diseases." (PMID 36186445, 2022). "Role of lncRNA MALAT1 in chronic lung diseases and other conditions." (PMID 36186445, 2022).
chronic lymphocytic leukemia (2 papers, 2015 to 2024). "Dysregulated expression of the long non-coding RNA MALAT1 has been implicated in the pathogenesis and progression of a variety of cancers, including hematological malignancies, but it has been poorly investigated in chronic lymphocytic leukemia (CLL)." (PMID 38255996, 2024).
chronic pancreatitis (2 papers, 2013 to 2017). A chronic inflammatory process causing damage and fibrosis of the pancreatic parenchyma. "RNA expression data obtained by Super-SAGE (serial analysis of gene expression) revealed 1.3- to 3.8-fold MALAT-1 overexpression in chronic pancreatitis, pancreatic adenocarcinomas and intraductal papillary mucinous tumors compared with normal pancreas tissue." (PMID 23717670, 2013). "MALAT1 fragments were detectable in human serum; however, their levels could not be used to distinguish PDAC tissues from chronic pancreatitis tissues and healthy control tissues." (PMID 28701723, 2017).
colitis (2 papers, 2023). Inflammation of the colon. "In parallel, MALAT1 KO mice were hypersensitive to DSS-induced acute colitis." (PMID 36768556, 2023). "MALAT1-knockout mice are hypersensitive to DSS-induced experimental colitis, and the absence of MALAT1 induces dysregulation of the intestinal mucosal barrier and disrupts intestinal homeostasis." (PMID 38130953, 2023).
congenital heart disease (2 papers, 2018 to 2022). A heart disease that is present at birth. "We evaluated the effects of tag single nucleotide polymorphisms (tag-SNPs) on MALAT1 gene in a Chinese population of children with congenital heart disease (CHD)." (PMID 29559566, 2018).
cutaneous melanoma (2 papers, 2017 to 2020). A primary melanoma arising from atypical melanocytes in the skin. "Further studies are required to validate the role of MALAT1, LINC00943 and LINC00261 in cutaneous melanoma." (PMID 32993558, 2020). "MALAT1, LINC00943, and LINC00261 were selected as hub genes and are responsible for the tumorigenesis and prognosis of cutaneous melanoma." (PMID 32993558, 2020). "MALAT1, LINC00943, and LINC00261 may be closely related to tumorigenesis in cutaneous melanoma." (PMID 32993558, 2020).
diabetic foot ulcer (2 papers, 2024 to 2025). "MALAT1 is a well-studied lncRNA, which is involved in the occurrence and development of various diseases, such as cancer, cerebral ischemic stroke, diabetic foot ulcer, etc.." (PMID 41170388, 2025). "This suggests the MALAT1-mediated signaling pathway probably contribute to the promoting effect of PRP-Exos on diabetic foot ulcer healing, potentially serving as a new target for diabetic foot treatment." (PMID 39498056, 2024).
disc degeneration (2 papers, 2020 to 2022). "Although no improved effect on the characterization of lumbar IDD was observed from X-ray, MALAT1 overexpression treatment improved the overall histological score shown by HE staining, which coincided with the degree of disc degeneration by MRI imaging." (PMID 32228440, 2020). "In vivo, MALAT1 overexpression attenuated the severity of disc degeneration in IDD model rats." (PMID 32228440, 2020).
Flavivirus Infections (2 papers, 2015 to 2021). Infections with viruses of the genus FLAVIVIRUS, family FLAVIVIRIDAE. "Previously, MALAT1 was shown to be upregulated by the UPR during flavivirus infection." (PMID 33585804, 2021).
follicular lymphoma (2 papers, 2023 to 2024). Follicular lymphoma is a form of non-Hodgkin lymphoma characterized by a proliferation of B cells whose nodular structure of follicular architecture is preserved. "The upregulation of MALAT1 was reported in follicular lymphoma, and high MALAT1 levels were associated with shorter progression-free survival (PFS)." (PMID 38255996, 2024). "In this study, we have performed a detailed characterization of the biological and clinical impact of MALAT1 deregulation in two types of indolent B cell lymphomas with different underlying pathobiological mechanisms, namely CLL and follicular lymphoma (FL)." (PMID 37803049, 2023). "Here, MALAT1 expression was analyzed using RNA-seq, microarrays or qRT-PCR in primary samples from clinico-biological subtypes of chronic lymphocytic leukemia (CLL, n = 266), paired Richter transformation (RT, n = 6) and follicular lymphoma (FL, n = 61)." (PMID 37803049, 2023).
gastrointestinal carcinomas (2 papers, 2020 to 2021). "For example, lncRNA MALAT-1 has been found to be upregulated in various malignant tumors, and upregulated MALAT-1 is remarkably linked to worse OS (overall survival) or DFS (disease-free survival) in individuals with gastrointestinal carcinomas." (PMID 33859998, 2021).
hilar cholangiocarcinoma (2 papers, 2022). A cholangiocarcinoma that arises from the junction, or adjacent to the junction, of the right and left hepatic ducts. "MALAT1 was shown to plays a role in the proliferation, migration, and invasion of human hilar cholangiocarcinoma (HCCA) cells." (PMID 35368523, 2022).
hyperandrogenism (2 papers, 2022 to 2024). Excessive secretion of androgens from the adrenal glands or gonads. "Altogether, these results suggested that there might be different pathophysiology involving MALAT1 in GCs in PCOS with or without hyperandrogenism." (PMID 38424234, 2024). "Based on the main difference in androgen levels, we hypothesized that MALAT1 expression in GCs might be downregulated in women with PCOS with hyperandrogenism, while MALAT1 level might be up-regulated in patients without hyperandrogenism and with high AMH." (PMID 35573984, 2022).
intracerebral hemorrhage (2 papers, 2022). A cerebrovascular disorder characterized by bleeding into one or both cerebral hemispheres including the basal ganglia and the cerebral cortex. "MALAT1 knockdown is reported to protect against intracerebral hemorrhage via miR-146a." (PMID 36700468, 2022).
intrahepatic cholangiocarcinoma (2 papers, 2024 to 2025). A carcinoma that arises from the intrahepatic bile duct epithelium in any site of the intrahepatic biliary tree. "It was reported that circRNA MALAT1 promoted the progression of intrahepatic cholangiocarcinoma by competing with miR-512-5p to bind to VCAM1, leading to upregulation of VCAM1 transcription and activation of PI3K/AKT signaling pathway." (PMID 40584619, 2025).
lupus nephritis (2 papers, 2022 to 2023). Glomerulonephritis in the context of systemic lupus erythematosus. "Expression of MALAT1 in patients with RA is related to disease activity and in SLE nephritis is considered as a potential discriminatory biomarker." (PMID 35203705, 2022). "The characteristics of CASC2 and MALAT1 suggest that they may affect the phenotype (i.e., histological class) of lupus nephritis." (PMID 37511572, 2023). "As a whole group, urinary MALAT1 and CASC2 levels were significantly increased in lupus nephritis compared to healthy controls (31.3 [IQR 21.5–61.9] vs. 9.3 [IQR 9.2–11.5] copies and 18.4 [IQR12.2–156.0] vs. 9.9 [IQR 9.7–12.1] copies, respectively; p < 0.0001 for both)." (PMID 37511572, 2023).
malignant pleural mesothelioma (2 papers, 2021 to 2025). A malignant neoplasm that arises from mesothelial cells in the pleura and shows a diffuse growth pattern. "A sensitivity of 88.89% and specificity of 66.67% for MALAT1 in diagnosing epithelial malignant pleural mesothelioma were reported, highlighting its potential cross-cancer diagnostic relevance." (PMID 40674376, 2025). "The aim of this study was to clarify the role of lncRNA metastasis-associated lung adenocarcinoma transcript 1 (MALAT1) in proliferation, migration, and invasion of malignant pleural mesothelioma (MPM) cells." (PMID 34761116, 2021).
mesothelioma (2 papers, 2018 to 2020). A usually malignant and aggressive neoplasm of the mesothelium which is often associated with exposure to asbestos. "Although only Malat1, from the ncRNAs mentioned, is an lncRNA for which a clear genetic link with tumorigenesis has been established, it is likely that ncRNAs function in mesothelioma as “cancer progenitors genes”." (PMID 29641489, 2018).
metastatic melanoma (2 papers, 2017 to 2021). A melanoma that has spread from its primary site to another anatomic site. "For example the lncRNA MALAT-1 has been associated with splicing, binds to SRSF1, at least in kidney tissue, and is overexpressed in metastatic melanoma." (PMID 28653984, 2017).